CD4 (CD4 molecule)
Diseases named in the same sentence as CD4 in open-access papers (continued):
Sharing a sentence is not in itself a finding about the gene and the disease.
sarcoidosis (continued). "A high proportion of lymphocytes and an elevated CD4+ to CD8+ T-lymphocyte ratio (CD4/CD8 ratio) in the bronchoalveolar lavage (BAL) fluid (BALF) indicate CD4+ cell-dominant inflammation in sarcoidosis." (PMID 32228530, 2020). "A proportion of CD4+ Vα2.3+ T-cells in BALF > 10.5% was highly specific for sarcoidosis, with a specificity of 97% and with a sensitivity of 36% (p < 0.0001)." (PMID 32111204, 2020). "In sarcoidosis, the lung homes up to ten times as many CD4+ T-cells as the peripheral blood, thus leading to an elevated CD4/CD8 ratio as measured in BAL fluid." (PMID 32722050, 2020). "Granuloma in sarcoidosis consists of a core of epithelial histiocytes and multinucleated giant cells surrounded by CD4 + T cells and fibroblasts." (PMID 33218322, 2020). "Advanced stage sarcoidosis is characterized by anergic CD4+ T lymphocytes expressing low levels of NF-ATc2 which is necessary for CD40L and ICOS expression." (PMID 33036432, 2020). "PBMCs of another 28 cases with sarcoidosis (14 cases with active sarcoidosis and 14 cases with stable sarcoidosis) and 18 healthy controls were sorted by magnetic beads to harvest CD4+ cells." (PMID 32508842, 2020). "This new lymphocyte subset called TH1/TH17 or TH17.1 has been found in higher numbers than the classical TH1 CD4+ T-cell subtype in BAL fluid of sarcoidosis patients." (PMID 33036432, 2020). "Multiple studies have established the importance of IFN-γ-producing CD4+ T helper (Th) cells in sarcoidosis, which have been traditionally designated as “Th1” cells." (PMID 32774332, 2020). "This biomarker therefore proved to be more useful for the diagnosis of LS, while the CD4/CD8 ratio is useful for the diagnosis of any type of sarcoidosis." (PMID 32760396, 2020). "Measurement of the ratio of CD4/CD8 T-cells has been used to differentiate sarcoidosis from other diseases since the 1980s." (PMID 32760396, 2020). "As a consequence of constant antigen exposure in both sarcoidosis and CBD, pathogenic CD4+ T cells develop an anergic and/or exhausted phenotype as a mechanism to decrease chronic T cell activation and subsequent inflammation." (PMID 32256501, 2020). "The association between a CD4/CD8-ratio > 3.5 and sarcoidosis was also confirmed in this study, which to our knowledge is the largest patient cohort showing this." (PMID 32111204, 2020). "A significantly increased CD4:CD8 T-cell ratio makes sarcoidosis more likely than other interstitial lung diseases." (PMID 33036432, 2020). "Granulomas were histologically similar to those observed in sarcoidosis with the recruitment of macrophages, CD4+ T lymphocytes with Th1 cytokine (IL-2 and IFNγ) production, and rare B lymphocytes." (PMID 32751786, 2020). "We found evidence of CD4 naïve T cell activation in sarcoidosis as well as enrichment of regulatory pathways, suggesting a persistent inflammatory response of potentially infectious or autoimmune origin." (PMID 33363531, 2020). "In comparison, the CD4/CD8-ratio > 3.5 had a lower specificity for sarcoidosis but a higher sensitivity." (PMID 32111204, 2020). "An accumulation of CD4+ T-lymphocytes in bronchoalveolar lavage fluid (BALF), resulting in an increased CD4/CD8 ratio (> 3.5), has been shown to associate with sarcoidosis." (PMID 32111204, 2020). "Our results showed that PBMCs of patients with sarcoidosis (n = 23) exhibit higher expression for activated CD4+CD25+T cells (mean ± SEM, 11.08 ± 5.32% as compared to healthy (n = 7) controls (mean ± SEM, 5.16 ± 2.71%, p < 0.05)." (PMID 30946009, 2019). "The findings revealed a high CD4/8 ratio and elevated lymphocyte differential count, which are findings consistent with sarcoidosis." (PMID 31515495, 2019). "Recently, it has been shown that Th17+/CD4+T cells are increased in sarcoidosis granulomatous tissue and peripheral blood." (PMID 30946009, 2019).
sarcoidosis (continued). "In sarcoidosis involving the lung, before the formation of granulomas, early lesions consist of alveolitis with a high proportion of activated CD4+ T-cells." (PMID 31731423, 2019). "Classically, sarcoidosis granulomas feature activated antigen presenting cells initiating adaptive immune responses with an increase in activated CD4+T-cells and Th1 mediated cytokines." (PMID 30946009, 2019). "The immune signature of sarcoidosis is the excessive immune response mediated by CD4+ type 1 helper-like cells (Th1-cells), including hyperactivation of Th1-cells and increased levels of Th1 cytokines." (PMID 31182092, 2019). "Previous studies of the lymphocyte profile in lymphadenopathy of sarcoidosis showed markedly different results for the CD4/CD8 ratio." (PMID 30452447, 2018). "Our study suggests Japanese sarcoidosis patients are a relatively homogenous cohort who present with high a CD4/CD8 ratio of T-lymphocytes in the lymph nodes." (PMID 30452447, 2018). "A remarkable feature of sarcoidosis is the compartmentalization of CD4 (+) T helper 1 (Th1) lymphocytes and activated macrophages in the affected organs to initiate the formation and maintenance of granulomas." (PMID 29510755, 2018). "When we applied both values (1.34 and 3.5) to our BAL CD4/CD8 ratio in sarcoidosis patients, 92.3% and 61.5% of patients fell above the cut-off value, respectively." (PMID 30452447, 2018). "Sarcoidosis is an inflammatory disease that typically is accompanied by an accumulation of activated CD4+ T cells in the lungs." (PMID 30485278, 2018). "There is some evidence that inhibition of CTLA-4 increases Th17 CD4+ cells in the peripheral blood, and there is also evidence that tissue samples consistent with sarcoidosis show increased infiltration of Th17 effector CD4+ cells in tissue." (PMID 30064495, 2018). "In 84% of sarcoidosis patients in our study, the CD4/CD8 ratio was higher in lymph nodes than the BAL." (PMID 30452447, 2018). "In sarcoidosis, lymphocytes in lymph nodes consisted of 56.6% CD4+ cells (SD: 13.8%), 9.60% CD8+ cells (SD: 5.1%), and 29.5% CD19+ cells (SD 15.0%) on average." (PMID 30452447, 2018). "In sarcoidosis, the CD4/CD8 ratio was significantly more elevated in lymph nodes than in bronchoalveolar lavage fluid (P<0.001), although both were strongly correlated." (PMID 30452447, 2018). "Although previous reports reported the lymphocyte profile in sarcoidosis lymph nodes including the CD4/CD8 ratio, the results were inconsistent among these reports." (PMID 30452447, 2018). "An elevated ratio of CD4/CD8 positive T-lymphocytes in bronchoalveolar lavage (BAL) fluid is suggestive for sarcoidosis diagnosis." (PMID 30452447, 2018). "In all the 14 TRBJ genes, TRBJ2-4 is significant highly expressed in CD4+ group than in CD8+ group and highly expressed in CD4+ group than in sarcoidosis group, while TRBJ2-5 is significant poorly expressed in CD8+ group than in tissue group." (PMID 29163767, 2017). "The comparison of the sarcoidosis and healthy control cohorts revealed an average of 18.7% and 7.9%, respectively, of apoptosing CD4+ T cells (p < 0.001)." (PMID 29234685, 2017). "Little is known regarding an extensive, longitudinal characterization of sarcoidosis CD4+ T cell adaptive immune function in subjects with disease progression compared to disease resolution." (PMID 29234685, 2017). "We have noted T regulatory cell-independent downregulation of the proximal T cell receptor pathway through Lck modulation in sarcoidosis CD4+ T cells." (PMID 29234685, 2017). "A central immunologic feature of CD4+ T cells in sarcoidosis is the spontaneous release of Th1 and Th2 cytokines —a phenotype indicative of active disease status in pulmonary sarcoidosis at both peripheral and local inflammation sites in the lungs." (PMID 29234685, 2017).
sarcoidosis (continued). "Investigation of PD-1 expression in sarcoidosis and healthy control cohorts revealed an average of 4.2% PD-1+CD4+ sarcoidosis T cells while the average percentage of PD-1+CD4+ T cells in the healthy control cohort was approximately 1.6% (p < 0.0001)." (PMID 29234685, 2017). "The granuloma in sarcoidosis is characterized by a core of monocyte-derived epithelioid histocytes and multinucleate giant cells with interspersed CD4+ T lymphocytes." (PMID 29163767, 2017). "Manual gating of cells using FlowJo revealed higher frequencies of CTLA-4+ (4.9%) and PD-1+ (35.7%) CD4+ T cells in BALF from a healthy individual compared to sarcoidosis patients of both phenotypes." (PMID 28955342, 2017). "In the sarcoidosis group, granulomas were mainly observed in the inner retinal layer filled with CD4+ cells and CD68+ cells, indicating the Th1 immune response." (PMID 29123243, 2017). "The observation of the reversible nature of T cell exhaustion in sarcoidosis advocates the use of immunotherapy to restore sarcoidosis CD4+ T cell function as a viable therapeutic target." (PMID 29234685, 2017). "This work demonstrates that sarcoidosis CD4+ T cells display an exhausted phenotype during progressive disease that is reversed among subjects experiencing disease resolution." (PMID 29234685, 2017). "Compared to healthy controls, sarcoidosis CD4+ T cells demonstrated reductions in Th1 cytokine expression, proliferative capacity (p < 0.05), enhanced apoptosis (p < 0.01), and increased PD-1 expression (p < 0.001)." (PMID 29234685, 2017). "Investigation of the Th1 immune response in sarcoidosis CD4+ T cells has revealed reduced proliferative capacity and cytokine expression upon TCR stimulation." (PMID 29234685, 2017). "Despite spontaneous secretion of Th1 (and Th2) cytokines such as IL-2 and IFN-γ, sarcoidosis CD4+ T cells demonstrate suboptimal Th1 cytokine production and proliferation following T cell receptor (TCR) stimulation during active disease." (PMID 29234685, 2017). "As a cohort, sarcoidosis CD4+ T cells demonstrated reduced cytokine expression and proliferative capacity upon TCR stimulation as well as upregulated PD-1 and a higher percentage of apoptotic cells at baseline (, –4)." (PMID 29234685, 2017). "We characterized sarcoidosis CD4+ T cell immune function in systemic and local environments among subjects undergoing disease progression compared to those experiencing disease resolution." (PMID 29234685, 2017). "We noted that when the percentage of TCR activated, proliferating sarcoidosis CD4+ cells were measured, only an average of 49.3% of cells proliferated whereas an average of 72.5% of healthy control CD4+ T cells proliferated after TCR stimulation (p < 0.05)." (PMID 29234685, 2017). "Sarcoidosis is characterized by an increased number of activated macrophage and CD4+ T cells and is therefore thought to be a Th1-driven inflammatory process." (PMID 29123243, 2017). "Analysis of BATF transcript and PD-1 protein expression in sarcoidosis CD4+ T cells revealed a positive relationship between BATF and PD-1, such that sarcoidosis subjects with high PD-1 upregulation also express higher levels of BATF (r = 0.56, p = 0.02)." (PMID 29234685, 2017). "The percentage of amino acid length 2 (p < 0.003), 5(p < 0.047), 16 (p < 0.0011), 18 (p < 0.0012), 19 (p < 0.013), 25 (p < 0.034), 26 (p < 0.033) were significantly higher in CD4+ group compared to sarcoidosis tissue group." (PMID 29163767, 2017). "Among sarcoidosis patients, however, expression of both receptors was primarily found in LS CD4+ T cells, indicating a higher degree of immune self-restriction compared to non-LS patients." (PMID 28955342, 2017). "To more carefully assess the capacity of sarcoidosis CD4+ T cells to produce cytokines, we compared spontaneous versus TCR-stimulated IL-2 and IFN-γ production." (PMID 29234685, 2017).
sarcoidosis (continued). "Because >90% of sarcoidosis subjects experience pulmonary involvement, we sought to characterize cytokine production, apoptosis, and PD-1 expression among bronchoalveolar lavage- (BAL-) derived sarcoidosis CD4+ T cells." (PMID 29234685, 2017). "The average percentage of PD-1+CD4+ T cells was significantly higher in sarcoidosis progressors than in healthy controls and sarcoidosis resolvers (p < 0.0001 and p < 0.05, resp)." (PMID 29234685, 2017). "The authors further showed that blockade of the PD-1 pathway, in vitro, restored the proliferative capacity of sarcoid CD4+ cells to the normal range, a pattern seen in spontaneous clinical resolution of sarcoidosis." (PMID 28031822, 2016). "The high CD4 we observed in VLF therefore means that it likely reflects the pathological features of sarcoidosis more directly than BALF." (PMID 27930546, 2016). "The major findings of this study were that the CD4/CD8 ratio and CD4 lymphocytes were elevated in VLF samples of patients with sarcoidosis." (PMID 27930546, 2016). "CD4+ T cell homeostasis plays important roles in granulomatous inflammatory activity and spontaneous resolution of sarcoidosis." (PMID 26845566, 2016). "In a potential link with anti-CTLA4 therapy and sarcoidosis development, bronchoalveolar lavage samples and lung biopsy specimens from patients with sarcoidosis also contain high numbers of Th17 effector CD4+ cells." (PMID 28031822, 2016). "CD45RA- Tregs have been reported to constitute the main subset during granuloma formation in a previous study, and other studies have shown that memory CD4+ T cells promote the remission of sarcoidosis." (PMID 26845566, 2016). "Sarcoidosis is a multi-system granulomatous disorder of unclear etiology characterized by the presence of CD4+ Th1-like cells that initiate granuloma formation in various tissues." (PMID 28031822, 2016). "In sarcoidosis patients, sarcoidosis increases the attraction of CD4+ T cells through the release of CCL4, either alone or together with Th1/Tc1-associated cytokines." (PMID 26587829, 2015). "This case report is important because it highlights the usefulness of the CD4/CD8 lymphocyte ratio in pleural effusion as an indicator of pleural involvement of sarcoidosis." (PMID 26271927, 2015). "In BAL CD4+ T cells, we noticed a significantly lower PPARα mRNA expression in sarcoidosis patients compared with HC." (PMID 25969669, 2015). "Since increased CD95 expression was observed on sarcoidosis CD45RO+ Tregs alongside impaired survival and increased apoptosis, we investigated apoptotic susceptibility of freshly isolated CD4+ T cells towards soluble CD95L." (PMID 26376720, 2015). "All subjects with active sarcoidosis showed a high intensity CD4+ lymphocytic alveolitis sustained by CD45RO+ T cells." (PMID 26240517, 2015). "The fractions of FoxP3+ CD4+ T cells and Th17 cells were both lower in sarcoidosis compared to controls (P = 0.017 and P = 0.011, resp)." (PMID 24882950, 2014). "Sarcoidosis is a multisystem disorder characterized by an accumulation of activated CD4+ T cells in the affected organs." (PMID 24656074, 2014). "The expression of TCR Vβ segments in CD8+ cells in sarcoidosis patients was analyzed in the same way as the CD4+ cells." (PMID 24656074, 2014). "The ratio of IFN-γ+ Th17/FoxP3+ CD4+ T cells was considerably increased in sarcoidosis compared to other DPLDs or HC." (PMID 24882950, 2014). "Later, the same group reported increased fractions of CD45RA−FoxP3bright CD4+ T cells in peripheral blood and CD4+ FoxP3+ cells in lymph nodes and granulomas of patients with active sarcoidosis." (PMID 24882950, 2014). "In BAL T cells from sarcoidosis patients, we identified 16 CD4+ T cell expansions in 271 analyses (5.9%) and 21 CD8+ expansions in 240 analyses (8.7%)." (PMID 24656074, 2014). "Fractions of BALF FoxP3+ CD4+ T cells and Th17 cells were lower in sarcoidosis compared to healthy controls." (PMID 24882950, 2014).
sarcoidosis (continued). "The fraction of FoxP3+ CD4+ T cells in BALF was significantly lower in patients with sarcoidosis compared to other DPLDs and HCs (median (IQR): 3.4% (2.1–4.8) versus 7.1% (4.4–12.6), P = 0.001 and versus 5.3% (4.4–7.0), P = 0.017)." (PMID 24882950, 2014). "The ratio between IFN-γ+ Th17 cells and FoxP3+ CD4+ T cells is markedly raised in patients with sarcoidosis in our study." (PMID 24882950, 2014). "Expression of CD27 and CD39 on FoxP3+ CD4+ T cells was higher in other DPLDs compared to sarcoidosis (P = 0.01 and P = 0.03, resp)." (PMID 24882950, 2014). "IFN-γ+ Th17 cells were highly correlated with Th1 cells (N = 23, rho = 0.64, and P = 0.001), and the ratio of IFN-γ+ Th17/FoxP3+ CD4+ T cells was prominently increased in sarcoidosis." (PMID 24882950, 2014). "Sarcoidosis patients have accumulations of activated CD4+ T cells in affected organs, such as the lungs." (PMID 24656074, 2014). "In particular, the majority of studies reported an increased frequency and impaired function of CD4+ CD25+ Tregs in the active phase of sarcoidosis compared with healthy controls, and significantly increased levels of Treg cells in BALF." (PMID 24177566, 2013). "It is now well established that T cells, and especially CD4+ helper cells, are mandatory in the development and maintenance of pulmonary granulomas in sarcoidosis." (PMID 24177566, 2013). "Patients with IPF have significantly higher CCR4 expression on BAL CD4 T cells compared to patients with other interstitial lung diseases such as sarcoidosis." (PMID 23705860, 2013). "In order to separate Behçet's disease and sarcoidosis, predictions based on all cells are very poor, better for CD4+ T cells and best for CD8+ T cells, for which no failed predictions are made when five or more measures are used." (PMID 24039568, 2013). "A second mechanism in sarcoidosis is that granulomas are characterized by local proinflammatory activated CD4 + T lymphocytes with Th1 profile (IFNγ, IL2) stimulating TNFα production by macrophages." (PMID 24373564, 2013). "There is a subpopulation of T cells (AV2S3+ (Vα2.3) CD4+ T cells) from BALF of HLA-DR∗0301 sarcoidosis patients which is unique to sarcoidosis." (PMID 26464848, 2013). "Absolute levels of both macrophages and T-lymphocytes, the key immune effector cells in sarcoidosis, are elevated in broncho-alveolar lavage fluid (BALF) from patients, and a lymphocytosis with a CD4/CD8 ratio >3.5 is virtually diagnostic." (PMID 23075428, 2012). "Increased proportions of oligoclonal CD4+ T cells were found in the BAL from patients with sarcoidosis, consistent with a MHC-restricted antigen-driven process." (PMID 22513006, 2012). "Other recent studies also support the immunosuppressive roles of VIP because VIP relieves collagen-induced arthritis and sarcoidosis by inducing CD4+CD25+Foxp3+ TReg cells from CD4+CD25− T cells." (PMID 22496728, 2012). "CD4+ Th17-type cells from a BD patient, a sarcoidosis patient, and a healthy donor significantly suppressed IL-17 production after exposure to infliximab." (PMID 22546542, 2012). "The majority of sarcoidosis patients exhibited reduced lymphocyte subset counts, including CD4 (57%), CD8 (54%), and CD19 cell counts (54%) as compared to healthy controls (p<4×10−10)." (PMID 20140091, 2010). "We found that the relative gene expression of IL-17 in CD4+ T cells was reduced in sarcoidosis patients, statistically significant (although weakly so) in patients with Löfgren's syndrome compared to healthy subjects." (PMID 20813038, 2010). "Twenty-two of the 31 sarcoidosis BAL samples produced a CD4+ response to at least one of the mycobacterial epitopes of ESAT-6, KatG, Ag85A, sodA, or HSP, compared to two of 14 PPD- controls (p = 0.00084) and five of nine NTM controls (p = 0.437)." (PMID 21092305, 2010). "Accumulation of BAL T-lymphocytes with prevalence of CD4+ cells is suggestive of sarcoidosis, whilst prevalence of CD8+ cells is suggestive of hypersensitivity pneumonitis." (PMID 20727133, 2010).